IAPP (islet amyloid polypeptide)
Description:
Amylin/IAPP is a glucoregulatory peptide hormone that plays an important role in the regulation of energy homeostasis. Selectively inhibits insulin-stimulated glucose utilization and glycogen deposition in muscle, while not affecting adipocyte glucose metabolism. IAPP function is mediated by the CALCR-RAMPs (AMYRs) receptor complexes (By similarity). Amylin can also bind CALCR receptor in the absence of RAMPs, although it is more selective for AMYRs (By similarity).
Synonyms: DAP; AMYLIN; IAP
Tractability: Small molecule: a structure with a bound ligand is known; a high-quality ligand is known; it has a high-quality binding pocket. Antibody: UniProt places it where antibodies can reach, with high confidence; its Gene Ontology location is reachable by antibodies, with high confidence; UniProt predicts a signal peptide or a membrane-spanning region. PROTAC: a small molecule that binds it is known.
Target class: Secreted protein
Gene: Protein-coding gene on chromosome 12 (21,354,959 to 21,379,980, forward strand). Ensembl gene ENSG00000121351.
Subcellular location: Secreted
Subcellular location (Human Protein Atlas): Vesicles; Predicted to be secreted
Pathways (Reactome):
Signal Transduction: Calcitonin-like ligand receptors; G alpha (s) signalling events
Developmental Biology: Regulation of gene expression in beta cells
Metabolism of proteins: Amyloid fiber formation
Gene Ontology:
Molecular function: identical protein binding; lipid binding; protein binding; receptor ligand activity; signaling receptor binding; amyloid-beta binding; hormone activity
Biological process: amylin receptor 1 signaling pathway; amylin receptor 2 signaling pathway; amylin receptor 3 signaling pathway; amylin receptor signaling pathway; positive regulation of calcium-mediated signaling; positive regulation of cAMP/PKA signal transduction; apoptotic process; cell-cell signaling; negative regulation of amyloid fibril formation; negative regulation of protein-containing complex assembly; positive regulation of apoptotic process; positive regulation of MAPK cascade; signal transduction; calcitonin family receptor signaling pathway; eating behavior
Cellular component: extracellular region; neuronal cell body
Genetic constraint (gnomAD): Loss-of-function variants: 1 observed, 2.89 expected, observed/expected ratio (o/e) 0.35, 90% interval 0.12 to 1.5. That is too few expected variants to judge how well the gene tolerates losing a copy. Missense variants: 102 observed, 96.07 expected, observed/expected ratio (o/e) 1.06, 90% interval 0.9 to 1.25. Synonymous variants: 35 observed, 37.87 expected, observed/expected ratio (o/e) 0.92, 90% interval 0.7 to 1.23.
Homologues: Orthologues: chimpanzee IAPP (98% identical), macaque IAPP (97% identical), dog IAPP (82% identical), guinea pig IAPP (70% identical), mouse Iapp (66% identical), rat Iapp (65% identical), tropical clawed frog iapp (51% identical). Paralogues in human: CALCB (35% identical), CALCA (22% identical).
Diseases named in the same sentence as IAPP in open-access papers:
IAPP is named in the same sentence as 91 diseases in open-access papers, as found by Europe PMC text mining. Sharing a sentence is not in itself a finding about the gene and the disease. The quoted sentences say what the papers report.
type 2 diabetes (266 papers, 2007 to 2026). "The deposition of cytotoxic human islet amyloid polypeptide (IAPP) aggregates is a hallmark feature of Type 2 Diabetes." (PMID 41772826, 2026). "A pathological hallmark of type II diabetes is the self-assembly of IAPP into β-sheet rich amyloid fibers, which is associated with β-cell impairment." (PMID 41926749, 2026). "Amyloid fibrils formed by the islet amyloid polypeptide cause pancreatic beta-cell damage, resulting in reduced insulin secretion and type 2 diabetes." (PMID 41844597, 2026). "The inherent aggregation propensity of this peptide hormone is not only associated with the pathogenesis of type 2 diabetes but also complicates the design of IAPP derivatives for the treatment of metabolic disorders." (PMID 41898461, 2026). "Researchers have utilized this tool to predict aggregation propensities for proteins implicated in AD (tau, amyloid-β), PD (α-synuclein), and Type 2 diabetes (islet amyloid polypeptide, IAPP)." (PMID 41303502, 2025). "This study employs computational epitope scanning to design antibody-like constructs targeting IAPP, demonstrating their utility in inhibiting aggregation, binding IAPP species, and detecting pathogenic aggregates in type 2 diabetes serum samples." (PMID 41395543, 2025). "Islet amyloid polypeptide (IAPP, amylin) is a peptide hormone that plays an important role in glucose homeostasis but has been implicated in the pathophysiology of type 2 diabetes and Alzheimer’s disease." (PMID 40046847, 2025). "β-cell death is a crucial component of type 2 diabetes, and the misfolding of IAPP is considered one of the causative factors." (PMID 38398700, 2024). "The deposition of islet amyloid polypeptide (hIAPP) fibrilsisa hallmark of β-cell death in type II diabetes." (PMID 38723619, 2024). "APRs are also found in IDPs associated with amyloid disease, such as Aβ, islet-associated polypeptide (IAPP) and αSyn involved in Alzheimer’s, type II diabetes and PD, respectively." (PMID 38170745, 2024). "The investigation of combinations involving GLP-1, gastric inhibitory polypeptide (GIP), islet amyloid polypeptide, glucagon, and leptin has revealed their potential to enhance weight loss in adults with obesity and type 2 diabetes." (PMID 39065679, 2024). "The islet amyloid derived from IAPP is associated with approximately 60% beta-cell deficit, increased beta-cell apoptosis, and islet failure in type 2 diabetes." (PMID 39081432, 2024). "For example, IAPP oligomers associated with type II diabetes are toxic by increasing Ca2+ influx and disrupting the mitochondrial membrane in pancreatic β-cells." (PMID 38378578, 2024). "The onset and progression of type 2 diabetes is linked to the accumulation and aggregation of human islet amyloid polypeptide (hIAPP) in the pancreas." (PMID 39615682, 2024). "β-cell dysfunction in type 2 diabetes is associated with pathological aggregates of IAPP that accumulate in pancreatic islets." (PMID 37813862, 2023). "Discussion: Despite the proximity of aSyn and IAPP in β-cells and the detected capacity of preformed aSyn fibrils to seed IAPP in vitro, it is still an open question if an interaction between the two molecules is of pathogenic significance for type 2 diabetes." (PMID 36793785, 2023). "The formation of IAPP deposits is intrinsically associated with type 2 diabetes (T2D) because more than 70% diabetic patients present this type of amyloid formation." (PMID 36291553, 2022). "For example, the single substitution S20G in the human islet amyloid polypeptide (IAPP) is associated with early onset of type II diabetes, while an array of single amino acid changes in Aβ are associated with familial Alzheimer’s disease." (PMID 35613051, 2022). "Amylin or islet amyloid polypeptide (IAPP) aggregation is associated with type 2 diabetes, where IAPP amyloid affects the islets of Langerhans accompanied by a decreased number of β-cell." (PMID 35327638, 2022).
type 2 diabetes (continued). "Notwithstanding essential physiological functions and therapeutic usage, IAPP is known for its high propensity to aggregate into insoluble amyloid fibrils that are associated with the pathogenesis of type 2 diabetes." (PMID 36262476, 2022). "Islet amyloid polypeptide (IAPP) fibrillation has been commonly associated with the exacerbation of type 2 diabetes prognosis." (PMID 35216095, 2022). "The islet amyloid polypeptide (IAPP) is a 37-residue aggregation-prone peptide hormone whose deposition as insoluble fibrils in the islets of Langerhans is associated with type II diabetes." (PMID 36262476, 2022). "The extracellular deposition of IAPP in the pancreatic islets is observed in over 90% of type 2 diabetic patients and correlates closely with the loss of function of pancreatic β-cells." (PMID 36262476, 2022). "The Winter group assessed the effects of a variety of crowding agents on human islet amyloid polypeptide (hIAPP), which is implicated in Type 2 Diabetes." (PMID 35883507, 2022). "Islet amyloid polypeptide (IAPP) is a proposed cause of the decreased beta-cell mass in patients with type-II diabetes." (PMID 33968989, 2021). "We also investigated the absorption spectra of Cu with Parkinson-associated α-syn, type II diabetes-related IAPP, or Aβ1-42." (PMID 34988394, 2021). "Amyloid deposits in pancreatic islets, mainly formed by human islet amyloid polypeptide (hIAPP) aggregation, have been associated with loss of β-cell mass and function, and are a pathological hallmark of type 2 diabetes (T2D)." (PMID 34088954, 2021). "Bri2 BRICHOS can prevent amyloid formation also of non-client peptides, including amyloid β peptide (Aβ) and islet amyloid polypeptide (IAPP), associated with AD and type 2 diabetes, respectively." (PMID 34330289, 2021). "For example, mutant Htt with polyQ extension in exon 1 aggregates in the cortex and striatum region of the brain while islet amyloid polypeptide (IAPP), an aggregate associated with type II diabetes, is found in the pancreas." (PMID 34632458, 2021). "The presence of amyloid fibrils in pancreatic β-cells, arising from the aggregation of human islet amyloid polypeptide (hIAPP), is a hallmark of type 2 diabetes (T2DM)." (PMID 34205510, 2021). "Another BACE2 target, implicated in type 2 diabetes (T2D), is hIAPP (human Islet Amyloid Polypeptide) an amyloidogenic protein, hallmark of T2D." (PMID 33926496, 2021). "IAPP is known for its propensity to self-assemble into cross-β amyloid structures, which are associated with the pathogenesis of type II diabetes." (PMID 34354242, 2021). "Islet amyloid polypeptide (IAPP) is an amyloid-forming peptide linked to the development of type-2 diabetes and has also been shown to be involved in AD pathology and vascular dementia." (PMID 31947546, 2020). "Pancreatic aggregates of human islet amyloid polypeptide (IAPP) represent a major histopathological hallmark of type 2 diabetes." (PMID 33013747, 2020). "Islet amyloid polypeptide (IAPP) associated with the pathology of type-2 diabetes misfolds and deposits in the β-cells of pancreas." (PMID 32724104, 2020). "The deposition of aggregated human islet amyloid polypeptide (hIAPP) in the pancreas, that has been associated with β-cell dysfunction, is one of the common pathological features of patients with type 2 diabetes (T2D)." (PMID 32183067, 2020). "For example, islet amyloid polypeptide (IAPP) was reported to promote the α-synuclein amyloid formation, which can explain why type-2 diabetes patients are susceptible to developing PD." (PMID 32456156, 2020). "Type 2 diabetes is one of the common amyloidosis and linked with the aggregation of human islet amyloid polypeptide (hIAPP)." (PMID 32117877, 2020). "The human islet amyloid polypeptide (hIAPP), also known as amylin, is a unique amyloidogenic precursor peptide, and a critical pathogenic biomarker of Type II diabetes." (PMID 31919432, 2020).
type 2 diabetes (continued). "Misfolding and aggregation of a small 37-residue peptide (islet amyloid polypeptide, IAPP) is associated with type-2 diabetes." (PMID 31338019, 2019). "The presence of amyloid deposits of human islet amyloid polypeptide (hIAPP) in islet β-cells has been associated with type 2 diabetes occurrence and islet graft failure." (PMID 30838043, 2019). "Type 2 diabetes (T2DM) is associated with aggregation of the human islet amyloid polypeptide (hIAPP) into cytotoxic amyloid species." (PMID 31836748, 2019). "Type 2 diabetes is associated with islet amyloid deposits derived from islet amyloid polypeptide (IAPP) expressed by β-cells." (PMID 31213603, 2019). "Islet amyloid deposition is increasingly seen as a pathogenic feature of type 2 diabetes mellitus, with the deposits containing the unique amyloidogenic peptide islet amyloid polypeptide (IAPP, also known as amylin)." (PMID 31118959, 2019). "Human islet amyloid polypeptide has long been a subject of research, both experimentally and theoretically, as the aggregation of this protein is believed to be the lead cause of type-II diabetes." (PMID 29023509, 2017). "For example fibrils of Sup35, an amyloid-like polypeptide in S. cerevisiae, and of human islet amyloid polypeptide (IAPP), associated with type II diabetes, both form the same class of dry steric zipper." (PMID 28937634, 2017). "In type 2 diabetes, the formation of islet amyloid consisting of islet amyloid polypeptide (IAPP) is associated with reduction in β-cell mass and contributes to the failure of islet cell transplantation." (PMID 27641459, 2016). "Pancreatic amyloid formation by islet amyloid polypeptide (IAPP) is a hallmark pathological feature of type 2 diabetes." (PMID 26840340, 2016). "The abnormal fibrillation of human islet amyloid polypeptide (hIAPP) has been implicated in the development of type II diabetes." (PMID 28074190, 2016). "IAPP can also aggregate and form amyloid deposits in the pancreas and, thus, is considered a pathological hallmark of type 2 diabetes." (PMID 27379014, 2016). "Aggregation of human islet amyloid polypeptide (hIAPP) into fibrils and plaques is associated with pancreatic β-cell loss in type 2 diabetes (T2D)." (PMID 26880502, 2016). "Amyloid deposits formed from islet amyloid polypeptide (IAPP) are a hallmark of type 2 diabetes mellitus and are known to be cytotoxic to pancreatic β-cells." (PMID 27607147, 2016). "In the previous studies, direct evidences for helical intermediate formation are shown for Aβ and IAPP associated with Alzheimer's and Type II diabetes, respectively." (PMID 25803428, 2015). "As IAPP is coexpressed, copackaged, and cosecreted with insulin by the pancreatic β-cells, the overproduction of insulin often associated with type II diabetes will lead to an increased release of IAPP." (PMID 26576436, 2015). "It has been recently reported that IAPP (associated with type II diabetes) helical oligomers are able to promote significant apoptosis of pancreatic β cells." (PMID 25803428, 2015). "Due to peripheral insulin resistance associated with type II diabetes, insulin and IAPP expression, maturation, and secretion by pancreatic β-cells are significantly increased." (PMID 26576436, 2015). "For example, it has been shown that helix-rich oligomers of islet amyloid polypeptide (IAPP) (associated with type II diabetes) are highly cytotoxic and they were able to induce apoptosis in pancreatic β cells." (PMID 25803428, 2015). "It was recently showed that the expression of hIAPP in mice with a β cell-specific autophagy defect results in an increase of β-cell dysfunction associated with IAPP-toxicity, suggesting a protective role of autophagy in type II diabetes." (PMID 26576436, 2015). "IAPP-amyloid is present in the islets of Langerhans in almost all individuals with type 2 diabetes, but is also seen in other conditions associated to beta cell stress, such as islet transplantation." (PMID 24671002, 2014).
type 2 diabetes (continued). "Cinnamon proanthocyanidins were also shown to be the major anti-diabetic components of a cinnamon water extract in the prevention of the misfolding of human islet amyloid polypeptide, a proposed causative factor for type 2 diabetes." (PMID 24349472, 2013). "IAPP plays a physiological role in glucose regulation; however, in certain species, IAPP can aggregate and this process is linked to β-cell death and Type II Diabetes." (PMID 24009497, 2013). "CN also inhibits the misfolding of human islet amyloid polypeptide which is regarded as a causative factor for type 2 diabetes mellitus." (PMID 24349472, 2013). "Islet amyloid polypeptide (IAPP, or amylin) is a hormone coexpressed with insulin by pancreatic islet β-cells and its abnormal aggregation into amyloid fibrils is a hallmark of type II diabetes." (PMID 23755253, 2013). "The study presented here focuses on the self-association of the type-2 diabetes mellitus related human islet amyloid polypeptide (hIAPP) in various crowded environments including network-forming macromolecular crowding reagents and protein crowders." (PMID 23922768, 2013). "The aggregation of human islet amyloid polypeptide (hIAPP or amylin) is associated with the pathogenesis of type 2 diabetes mellitus." (PMID 22693597, 2012). "The amyloid fibrils formed by islet amyloid polypeptide (IAPP) are associated with type II diabetes." (PMID 23133593, 2012). "The fatal mutation of S20G human IAPP was reported to lead to early onset of type II diabetes and high tendency of amyloid formation in vitro." (PMID 23133593, 2012). "In Asian populations a single point mutation in the IAPP gene (IAPPS20G) has been linked to an increased risk to develop type 2 diabetes." (PMID 21695120, 2011). "It is suggested that type 2 diabetes is heterogeneous and that in one major subtype aggregation of IAPP into amyloid fibrils is determining the progressive loss of β-cells." (PMID 21486192, 2011). "Over-production of insulin, often seen in type 2 diabetes as a response to insulin resistance, is associated with increased release also of IAPP since these two β-cell products are normally regulated in parallel." (PMID 21486192, 2011). "It is worth noting that replicating β-cells are more susceptible to cell death induced by islet amyloid polypeptide that accumulates in β-cells in patients with type 2 diabetes." (PMID 22140505, 2011). "One hallmark of type 2 diabetes is the formation of amyloid in the pancreatic islet, which is composed of human islet amyloid polypeptide (90%) and lipid molecules (10%)." (PMID 19360098, 2009). "Peptide IAPP (islet amyloid polypeptide) 9-17 is one of the HLA-A*0201-restricted T cell epitopes in T1D patients, but IAPP is more of a type 2 diabetes risk factor in the process of ß cell apoptosis." (PMID 19471607, 2008). "Type 2 diabetes mellitus is a multifactorialdiseaseassociated with insulin resistance and pancreatic β-cell dysfunction.Interestingly, this disease has also been associated with the aggregationof islet amyloid polypeptide (IAPP or amylin)." (PMID 40727756, 2025). "Furthermore, the development of type 2 diabetes in humans is associated with the formation of cytotoxic amyloid fibrils, which consist of islet amyloid polypeptide (IAPP), also called amylin." (PMID 38829477, 2025). "Alzheimer’s disease and Type 2 diabetes are two epidemiologically linked diseases which are closely associated with the misfolding and aggregation of amyloid proteins amyloid-β (Aβ) and human islet amyloid polypeptide (hIAPP), respectively." (PMID 38338914, 2024). "Islet amyloid polypeptide, has direct toxicity to islet B cells, mediates local inflammatory reaction, leading to pancreatic islet dysfunction, an important pathological factor causing type 2 diabetes mellitus." (PMID 37249284, 2023). "Type II diabetes is intimately linked to amyloidosis of the protein hormone IAPP in the islets of Langerhans in insulin producing beta-cells, the same cell that produces IAPP." (PMID 36998202, 2023).